ITGB2 (integrin subunit beta 2)
Diseases named in the same sentence as ITGB2 in open-access papers (continued):
Sharing a sentence is not in itself a finding about the gene and the disease.
colon carcinoma (6 papers, 2020 to 2024). "The relationship between LINC01272 and ITGB2 was analysed with the RNA-Seq dataset GEPIA, and the results showed that LINC01272 was positively associated with ITGB2 in colon cancer, rectal cancer and CRC (P<0.001)." (PMID 34093798, 2021). "Colon cancer outcomes are associated with changes in MDSC infiltration, and therefore LCP1, ITGB2, and IKZF1 may be novel targets for immunotherapy." (PMID 36230637, 2022). "Through further experimental verification, we revealed that the expression of LCP1, ITGB2, and IKZF1 were significantly upregulated in right-sided colon cancer samples compared to that of left-sided colon cancer samples (p < 0.05)." (PMID 36230637, 2022).
diabetic nephropathy (6 papers, 2021 to 2025). "Additionally, bioinformatics analysis illuminated that other diseases which were associated with ITGB2 included lupus nephritis and diabetic nephropathy." (PMID 36978098, 2023). "Hub genes (FPR3, C3AR1, CD14, ITGB2, RAC2 and ITGAM) related to iron death in diabetic nephropathy were obtained through gene expression differential analysis between different subtypes." (PMID 34735495, 2021). "Our study explored the same platform GEO dataset for diabetic nephropathy bioinformatics analysis and identified eight potential key genes (TYROBP, ITGB2, CD53, IL10RA, LAPTM5, CD48, C1QA, and IRF8), screened eight transcription factors, and identified 93 miRNA nodes." (PMID 37113991, 2023). "Finally six Hub genes related to iron death in diabetic nephropathy were obtained, including FPR3, C3AR1, CD14, ITGB2, RAC2 and ITGAM." (PMID 34735495, 2021).
hepatocellular carcinoma (6 papers, 2007 to 2025). A malignant tumor that arises from hepatocytes. "ALDH2, ITGB2, LGALS3, CTSB, PRDX1, and CD14 were identified as multifunctional proteins that are associated with tumorigenesis, damage, cancer cell death, necrosis, fibrosis, hepatocellular carcinoma, steatosis, and inflammation." (PMID 29481576, 2018). "Further, we targeted the ITGB2 gene using CRISPR-Cas9 technology in A549 cells and in the human hepatocellular carcinoma cells HepG2, a liver cell line exhibiting epithelial-like morphology, being the liver an organ that arises from the embryonic endoderm as the lung." (PMID 37215577, 2023).
lymphoma (6 papers, 2007 to 2026). A malignant (clonal) proliferation of B- lymphocytes or T- lymphocytes which involves the lymph nodes, bone marrow and/or extranodal sites. "We identified a new association of CD151 with ITGB2 in lymphoma cells that is important for cell spreading." (PMID 40464949, 2025). "Immunoprecipitation-mass spectrometry analysis of CD151 protein complexes identified integrin beta 2 (ITGB2) as new interaction partner in lymphoma cells." (PMID 40464949, 2025). "BJAB lymphoma cells express low levels of ITGAL as partner of ITGB2 in LFA-1, and intermediate levels of ITGAM." (PMID 40464949, 2025).
prostate carcinoma (6 papers, 2015 to 2024). A carcinoma that arises from epithelial cells of the prostate gland. "TRPM2, ITGB2, and ETS2 are located on chromosome 21 and are associated with breast, ovarian, and prostate cancers." (PMID 38803515, 2024). "HES6 knockdown influenced the expression of two cell migration-associated genes—metalloproteinase 7 (MMP7) and ITGB2 —as well as STEAP4, which was previously implicated in prostate cancer cellular proliferation." (PMID 25864518, 2015). "However, it has been reported that PRDM4 interacts with the WW domains of YAP to mediate the expression of ITGB2 and other YAP target genes, inducing cell invasion and tumorigenesis in prostate cancer." (PMID 33846573, 2021).
viral infection (6 papers, 2008 to 2025). "We screened for differentially expressed genes associated with bacterial or viral infections (IFI44L, PI3 and ITGB2) and compared the expression levels of the genes in different infection subgroups." (PMID 41050698, 2025). "Differential expressed genes analysis of IFI44L, PI3 and ITGB2 in bacterial and viral infections." (PMID 41050698, 2025).
acute myeloid leukemia (5 papers, 2022 to 2026). Acute myeloid leukemia (AML) is a group of neoplasms arising from precursor cells committed to the myeloid cell-line differentiation. "For example, the high expression of ITGB2 is accompanied by high drug resistance and poor prognosis in acute myeloid leukemia (AML)." (PMID 36035147, 2022). "ITGB2 was identified to be the key immune-related gene in acute myeloid leukemia patients, while the high expression of ITGB2 was related to the poor prognosis of acute myeloid leukemia patients." (PMID 36362654, 2022). "It is reported that ITGB2 had a powerful influence on immune cell infiltration into the acute myeloid leukemia (AML) tumor microenvironment." (PMID 36699448, 2022).
Alzheimer disease (5 papers, 2015 to 2024). A progressive, neurodegenerative disease characterized by loss of function and death of nerve cells in several areas of the brain leading to loss of cognitive function such as memory and language. "Furthermore, ITGB2 was identified to be closely associated with apoptosis in patients with Alzheimer’s disease." (PMID 32894197, 2020).
osteosarcoma (5 papers, 2006 to 2026). A usually aggressive malignant bone-forming mesenchymal neoplasm, predominantly affecting adolescents and young adults. "Additionally, previous research also reported that ITGB2 was upregulated in osteosarcoma, which could drive tumor metastasis via the ITGB2/FAK pathway." (PMID 36980477, 2023).
periodontal disease (5 papers, 2015 to 2025). "Among the 92 inflammation-related genes evaluated using the TaqManTM Array Plate Human Inflammation Kit (Thermo Fisher Scientific, Waltham, MA, USA), four genes (TNFSF13B, ITGB2, ANXA5, and ANXA3) showed significant differential expression in patients with active periodontal disease." (PMID 40004451, 2025). "The fact that some patients in our study developed periodontal diseases compared to other patients who did not may be explained by the degree of ITGB2 expression on the surface of their leukocytes, despite the fact that both study groups suffered from chromosome 21 trisomy." (PMID 31772502, 2019).
renal carcinoma (5 papers, 2018 to 2022). A carcinoma arising from the epithelium of the renal parenchyma or the renal pelvis. "Another study showed that ITGB2 downregulated Treg cells levels and inhibited renal carcinoma development." (PMID 34136377, 2021). "ITGB2 was reported to be involved in cellular adhesion and ECM remodeling in patients with renal cancer." (PMID 32894197, 2020). "ITGB2 has also been reported to be negatively correlated with eGFR in patients with CKD and involved in cell adhesion and extracellular matrix remodeling in renal cancer." (PMID 35836957, 2022).
Cerebral ischemia (4 papers, 2020 to 2023). Restriction of arterial blood supply to the brain associated with insufficient oxygenation to support the metabolic requirements of the tissue. "Then, according to our previous omics data from the tMCAO mice model, we found that Itgb2 might play an important role in cerebral ischemia." (PMID 37063847, 2023).
colitis (4 papers, 2016 to 2023). Inflammation of the colon. "β2-integrins (ITGB2) are required for IL-1β dependent induction of IL-22 by ILC3s, ITGB2 deficiency is associated with impaired IL-22 responses in colitis." (PMID 37016023, 2023).
gastric cancer (4 papers, 2007 to 2022). A primary or metastatic malignant neoplasm involving the stomach. "At present, the relationship between ITGB2 and gastric cancer has not been thoroughly studied." (PMID 34367971, 2021).
ischemic stroke (4 papers, 2020 to 2025). A stroke disorder caused by obstruction of blood flow to the brain, due to thrombotic (local blood clot formation) or embolic (due to a blood clot or other material traveling from another site) event. "The sc_S4 of Itgb2+ cells were mainly involved in the cell cycle and RNA splicing process, which we inferred was inextricably related to the proliferation and differentiation of inflammatory cells and the various types of cells performing their functions in the early phase of ischemic stroke." (PMID 37063847, 2023). "ITGB2 participates in immune activities related to glioblastoma, influencing B cells, CD4+ T cells, macrophages, neutrophils, and dendritic cells, and plays roles in energy metabolism, cell cycle regulation, angiogenesis, and neuronal myelin formation and repair after ischemic stroke." (PMID 41459526, 2025).
lung adenocarcinoma (4 papers, 2018 to 2025). A carcinoma that arises from the lung and is characterized by the presence of malignant glandular epithelial cells. "The mRNA expression and protein levels of ITGB2 are lower in lung adenocarcinoma tissues compared to normal tissues." (PMID 41340014, 2025). "The relative expression levels of AGRN and ITGB2 in lung adenocarcinoma samples were significantly different from those in normal tissues (p for Wilcoxon tests < 0.05)." (PMID 41340014, 2025). "Itgb2 has been identified as a key oncogene in many human cancers, such as clear cell renal cell carcinoma, high-grade serous ovarian cancer, and lung adenocarcinoma." (PMID 33679872, 2020). "For the significant proteins identified in the observational analyses, Agrin (AGRN), CD5 antigen‐like (CD5L), glucosamine‐6‐phosphate isomerase 1 (GNPDA1), integrin beta‐2 (ITGB2) and neuronal‐specific septin‐3 (SEPTIN3) remained associated with lung adenocarcinoma in the two‐sample MR analyses." (PMID 41340014, 2025).
nephrotic syndrome (4 papers, 2015 to 2022). A collection of symptoms that include severe edema, proteinuria, and hypoalbuminemia; it is indicative of renal dysfunction. "Tissue analysis of kidney in rat model of nephrotic syndrome (NS) revealed increased expression of ITGB2 (CD18) in cytotoxic T lymphocytes, NK cells and monocytes." (PMID 35812314, 2022).
autoimmune disease (3 papers, 2016 to 2020). A disorder resulting from loss of function or tissue destruction of an organ or multiple organs, arising from humoral or cellular immune responses of the individual to their own tissue constituents. "Finally, ITGB2 might be a potential candidate in an autoimmune disease that might be contributing to the inflammatory responses." (PMID 29317699, 2018).
endometriosis (3 papers, 2023 to 2025). The growth of functional endometrial tissue in anatomic sites outside the uterine body. "Nine altered pathways linked with ITGB2 were involved in the immune response, with 7 of them primarily upregulated, indicating that ITGB2 could be associated with immune dysregulation in endometriosis." (PMID 39666559, 2025). "Lifitegrast, an antagonist of ITGB2, demonstrated its efficacy in alleviating endometriotic lesion growth, indicating its potential to be repurposed for endometriosis." (PMID 39666559, 2025). "Together, these results demonstrate the therapeutic efficacy of Lifitegrast in treating endometriosis in an ITGB2‐dependent manner." (PMID 39666559, 2025). "Lifitegrast, a clinically approved ITGB2 inhibitor, may be repurposed as an endometriosis treatment." (PMID 39666559, 2025). "In addition to the expression dysregulation analysis, pathway enrichment analysis was conducted to explore the role of ITGB2 in endometriosis." (PMID 39666559, 2025). "Consequently, we identified integrin subunit beta 2 (ITGB2) as a potential druggable target for endometriosis." (PMID 39666559, 2025). "Interestingly, Il6, Mmp3, Itgb2, and Vegfa, a group of genes known to play a role in endometriosis, increased in the developing lesion tissues in all groups compared with control I and α minced endometrial pieces." (PMID 39836475, 2025). "Indeed, Lifitegrast suppressed endometriotic growth in preclinical murine endometriosis models, demonstrating a novel role for ITGB2 in endometriosis pathology." (PMID 39666559, 2025). "Using an artificial intelligence (AI)‐driven target discovery platform, two unreported therapeutic targets, guanylate‐binding protein 2 (GBP2) and hematopoietic cell kinase (HCK) are identified, along with a drug repurposing target, integrin beta 2 (ITGB2) for the treatment of endometriosis." (PMID 39666559, 2025). "The increased expression of ITGB2 had been previously reported in endometriosis tissues compared with normal tissues, and high C3AR1 expression might be used as a diagnostic factor for the endometriosis-associated malignant phenotype." (PMID 36660246, 2023). "Furthermore, Lifitegrast, an approved ITGB2 inhibitor, was identified as a candidate drug through PandaOmics that may have therapeutic value in treating endometriosis." (PMID 39666559, 2025). "Compared with the control group, high C3, VCAM1, ITGB2, and C3AR1 expression had statistical significance in endometriosis among the hub DEIRGs." (PMID 36660246, 2023). "The expression of GBP2, HCK, and ITGB2 in matched eutopic endometrium and endometriosis lesions was not explored due to sample constraints." (PMID 39666559, 2025).
inflammatory bowel disease (3 papers, 2024 to 2025). A spectrum of small and large bowel inflammatory diseases of unknown etiology. "In murine models of inflammatory bowel disease (IBD), elevated ITGB2 expression has been observed, while its suppression exacerbates disease pathology." (PMID 40506039, 2025).
liver cancer (3 papers, 2020 to 2024). An epithelial or non-epithelial malignant neoplasm that arises from the liver. "CD44 facilitates transendothelial migration of liver cancer cells by promoting expression of integrin subunit beta 2 (Itgb2)." (PMID 37174657, 2023).
liver fibrosis (3 papers, 2017 to 2026). "ITGB2 is upregulated in the peripheral blood and skin of SSc patients, correlating positively with liver fibrosis and post‐COVID‐19 lung complications." (PMID 40165483, 2025). "Taken together, this study demonstrates that primed MSCs attenuate schistosomiasis liver fibrosis by enhancing macrophage subset switch and efferocytosis via Itgb2-Rac1 axis, which offers novel insights into the therapeutic targets of MSC-based anti-fibrotic therapy." (PMID 41667438, 2026).
lymph node metastasis (3 papers, 2020 to 2025). "ITGB2 expression was significantly associated with tumor size, tumor stage, grade, lymph node metastasis, and vascular invasion." (PMID 40071217, 2025). "ITGB2 is significantly upregulated in serum exosomes in patients with papillary thyroid cancer with lymph node metastasis." (PMID 33335550, 2020).
nasopharyngeal carcinoma (3 papers, 2022 to 2023). A carcinoma arising from the nasopharyngeal epithelium. "Then, we explored the prognostic value of STC2/ITGB2/SOX6 in nasopharyngeal carcinoma." (PMID 33797657, 2022). "We not only found its high expression in primary nasopharyngeal carcinoma tissues and lymph-node metastatic tissues, but also found that STC2-mediated regulation of EMT and glycolysis traits was partially realized through the modulation of ITGB2/FAK/SOX6 signaling." (PMID 33797657, 2022).
osteoarthritis (3 papers, 2022 to 2025). A noninflammatory degenerative joint disease occurring chiefly in older persons, characterized by degeneration of the articular cartilage, hypertrophy of bone at the margins and changes in the synovial membrane. "Transcriptomics studies have identified integrin receptor β2 subunit (ITGB2) as a core gene in osteoarthritis (OA), strongly linked to osteoclast function in the subchondral bone." (PMID 40730513, 2025). "Considering OA, our finding came in accordance with a previous study which revealed an increase in ITGB2 gene expression levels in a rat model of shift–induced osteoarthritis-like changes at temporomandibular joint." (PMID 37644537, 2023). "Moreover, inhibition of the ITGB2 signalling pathway slows subchondral bone remodelling in osteoarthritis by inhibiting osteoclast differentiation, offering a potential strategy for targeted therapeutic interventions." (PMID 40730513, 2025). "In brief, we found four hub genes, i.e., CD4, SELL, ITGB2, and CD52 that are potential diagnostic biomarkers which may contribute to the diagnosis of osteoarthritis and provide further insight into the underlying molecular mechanisms for OA risk genes." (PMID 36468029, 2022). "However, ITGB2 or CD18 has received little attention in the study of osteoarthritis." (PMID 36468029, 2022). "Meanwhile, q-PCR results of clinical samples showed that four genes (CD4, SELL, ITGB2, and CD52) were upregulated in human primary synoviocytes compared with non-osteoarthritis samples." (PMID 36468029, 2022).
pancreatic adenocarcinoma (3 papers, 2004 to 2018). "For example, cholangiocarcinoma (CHOL) overexpresses a large variety of subunits (e.g. ITGAV, ITGA1, ITGA4, ITGA5, ITGA11, ITGB1, ITGB2, ITGB6), whereas, the equally deadly pancreatic adenocarcinoma (PAAD) overexpresses a very limited set of integrins, including ITGA6 and ITGB4." (PMID 30046394, 2018).
papillary thyroid cancer (3 papers, 2020 to 2024). "The ITGB2 genetic variants have been associated with the risk of papillary thyroid cancer, Behçet’s disease, and coronary heart disease." (PMID 37644537, 2023). "In particular, the ITGB2 promoter SNP rs2070946 was associated with the development of papillary thyroid cancer." (PMID 37644537, 2023).
schistosomiasis (3 papers, 2018 to 2026). An infectious disease caused by parasitic trematodes of the genus Schistosoma that colonize human blood vessels and release eggs that can cause granulomatous reactions leading to acute (swimmer's itch or acute schistosomiasis syndrome) or chronic disease. "To investigate the molecular role of CD18 on monocyte progenitor cells and alternative activation of macrophages during schistosomiasis, we used a mice model that expresses low levels of CD18 (CD18low), thus resembling humans with moderate ITGB2 deficiency." (PMID 36263057, 2022).
staphylococcus aureus infection (3 papers, 2023 to 2025). An infectious process in which the bacteria Staphylococcus aureus is present. "This suppression, along with reduced expression of integrins such as ITGAM and ITGB2 (integrin), likely contributed to the enrichment of infection-related pathways, including those associated with prion disease and Staphylococcus aureus infection." (PMID 41155303, 2025). "Within Cell adhesion Molecules (CAMs), the adaptive immune gene ITGB2 regulates both Staphylococcus aureus infection and complement and coagulation cascades." (PMID 37849501, 2023). "KEGG enrichment identified neutrophil-mediated defense mechanisms as central shared pathways, with Staphylococcus aureus infection (C1QA/B/C, P = 2.2×10-11) and neutrophil extracellular trap formation (ITGAM/ITGB2, P = 7.3×10-10) exhibiting strongest associations." (PMID 41199823, 2025).
Amoebiasis (2 papers, 2019 to 2022). "For example, among amoebiasis pathway-related proteins, integrin beta-2 (ITGB2), heat shock protein beta-1 (HSPB1), LCN2, leukocyte elastase inhibitor (SERPINB1), laminin subunit alpha-4 (LAMA4), and fibronectin (FN1) have been found to be correlated with immunity." (PMID 36387401, 2022). "In addition, the up-regulated DEGs were significantly enriched in 12 pathways such as NF-kappa B signaling pathway including LYN, LY96, CCL4, CD14; ECM-receptor interaction pathway including CD44, COL6A3, COL1A2, FN1 and Amoebiasis pathway including COL1A2, ITGB2, CD14, FN1." (PMID 31355054, 2019).
B cell lymphomas (2 papers, 2023 to 2025). "We identified integrin beta 2 (ITGB2, CD18) as a novel binding partner of CD151 in B cell lymphoma." (PMID 40464949, 2025). "Here we report CD151 expression and its molecular interaction with ITGB2 in B cell lymphomas." (PMID 40464949, 2025).